FLT3 (fms related receptor tyrosine kinase 3)
Diseases named in the same sentence as FLT3 in open-access papers (continued):
Sharing a sentence is not in itself a finding about the gene and the disease.
acute myeloid leukemia (continued). "The inhibition of FLT3 signaling by sorafenib or quizartinib with the concomitant use of PRI-724 to block the transcriptional activity of β-catenin improved the effects against acute myeloid leukemia stem cells." (PMID 37445628, 2023). "In aberrant hematopoiesis, such as in acute myeloid leukemia (AML), upregulated expression of DLX1 has been recorded as a downstream effect of activating mutations of fms-like tyrosine kinase 3 (FLT3), a frequent genomic alteration (~30%) that accompanies AML phenotypes." (PMID 37835497, 2023). "In acute myeloid leukemia, the FLT3 gene (which encodes a class III receptor tyrosine kinase that regulates hematopoiesis) is frequently mutated, and FLT3-mutant cells are able to promote the Wnt/β-catenin pathway by activating Integrin αvβ3/PI3K/Akt/GSK-3β signaling." (PMID 37445628, 2023). "The potential drug-drug interactions of midostaurin may impact the choice of antifungal (AF) prophylaxis in FLT3-positive acute myeloid leukemia (AML) patients." (PMID 35736066, 2022). "In acute myeloid leukemia, molecular genetics abnormalities, particularly NPM1 and FLT3 mutations, have a recognized prognostic role in the ELN risk classification and guide treatment decisions, especially since the availability of FLT3-targeted drugs." (PMID 36230640, 2022). "Recent data demonstrated that mutations of these two genes have opposite consequences on PARPi sensitivity in acute myeloid leukaemia (AML) cells expressing oncogenic tyrosine kinases (e.g., mutated FLT3 or JAK2), which are characterised by high endogenous levels of DNA DSB." (PMID 36612003, 2022). "FLT3 overactivation is the most common form of genetic alteration in acute myeloid leukemia (AML)." (PMID 36555494, 2022). "Fms-like tyrosine kinase 3 (Flt3) is a target of TKIs used for acute myeloid leukemia treatment." (PMID 34903561, 2022). "FMS-like tyrosine kinase 3 (FLT3) is an attractive therapeutic target in acute myeloid leukemia." (PMID 35387260, 2022). "FLT3-internal tandem duplication (ITD), which activates its protein function constitutively, is one of the most common gene mutations found in patients with acute myeloid leukemia (AML)." (PMID 36010999, 2022). "BiTE for acute myeloid leukemia (AML) targets proteins expressed on most AML blasts, such as CD33 and CD123, and cell surface proteins that are often overexpressed or mutated on AML blasts, such as FLT3." (PMID 36232824, 2022). "Here we describe how the combination of MS-based (phospho)proteomics with literature-derived signaling networks may help to identify new therapeutic targets to revert the chemoresistance of FLT3-dependent acute myeloid leukemia." (PMID 33925552, 2021). "In addition, in patients with acute myelocytic leukemia, the overexpression of IGF2BP2 indicates poor survival, and IGF2BP2 expression is associated with mutations in FLT3-ITD and IDH1, which are also indicators of poor prognosis." (PMID 33628845, 2021). "In an open-label, randomized phase III trial at 7 hospitals in China, 202 patients with an FLT3-ITD acute myeloid leukemia, who underwent an aHSCT, were randomly assigned (1:1) to Sorafenib maintenance (400 mg orally twice daily) or non-maintenance (control) at 30–60 days post transplantation." (PMID 34070902, 2021). "In general, the prognosis of acute myeloid leukaemia (AML) patients with FLT3‐ITD is poor." (PMID 33932107, 2021). "Until recently, no effective targeted therapies for FLT3-mutated (FLT3mut+) relapsed/refractory (R/R) acute myeloid leukemia (AML) were available in Japan." (PMID 34363558, 2021). "Subsequently, combined with complementary metabolomic and gene-expression analysis, they indicated that there is a metabolic dependency relationship between glutamine metabolism and FLT3 internal tandem duplication (FLT3ITD) cells in acute myeloid leukemia (AML) after FLT3 TK inhibition." (PMID 34598686, 2021).
acute myeloid leukemia (continued). "Moreover, FMS-like tyrosine kinase 3 (FLT3) internal tandem duplication (ITD) is the most common genetic alteration observed in patients with acute myeloid leukemia." (PMID 34208645, 2021). "Furthermore, inhibition of their upstream regulators BCR-ABL1 (in chronic myeloid leukemia cells) and FLT3-ITD (in acute myeloid leukemia cells) plus hydroxyurea produced favorable results." (PMID 34298678, 2021). "This disruptive approach to the use of the dPCR technique could be applied similarly for the detection of other ITD on genes of interest in the field of cancer (e.g. FLT3-ITD in acute myeloid leukemia)." (PMID 33718245, 2021). "Additionally, crotonoside has been reported to be capable of suppressing acute myeloid leukemia via inhibiting Fms-like tyrosine kinase 3 (Flt3) and HDAC3/6 pathways." (PMID 33182776, 2020). "Furthermore, ATX is copiously expressed in CD34+ HSCs and FLT3-ITD+ acute myeloid leukemia (AML) cells." (PMID 32188052, 2020). "Other studies revealed that C-18 ceramide and the mitochondria-targeted ceramide analog LCL-461 induced lethal mitophagy in head and neck squamous cell carcinoma and FLT3-ITD (Fms-like tyrosine kinase 3-internal tandem repeat)-positive acute myeloid leukemia (AML) cells, respectively." (PMID 31671879, 2019). "Mutations at the JMD or TKD of FLT3 induce constitutive kinase activation that is independent of FL, and occurs in approximately one-third of acute myeloid leukemia (AML) patients." (PMID 31692922, 2019). "Research has shown that FMS-like tyrosine kinase 3 (FLT3) may be a vital drug target for acute myeloid leukemia (AML)." (PMID 31619996, 2019). "PD-L1 expression level, which was determined by PCR as the ratio of transcription variants v1/v2, is an important negative prognostic factor for the acute myeloid leukemia, specifically for patients with FLT3-ITD and concomitant NPM1 mutation." (PMID 31185600, 2019). "PTPRJ is a negative regulator of FLT3 signaling that is linked to ROS formation and DNA damage, and deletion of PTPRJ promoted myeloproliferative disease in FLT3-internal tandem duplication acute myeloid leukemia." (PMID 31384238, 2019). "FMS-like tyrosine kinase 3 (FLT3) is a key driver of acute myeloid leukemia (AML)." (PMID 31819100, 2019). "Moreover, ponatinib is being tested in clinical trials to evaluate its activity in FLT3-internal tandem duplication (ITD) acute myelogenous leukemia, head and neck cancers, certain type of lung cancer, gastrointestinal stromal tumours and other malignancies." (PMID 30423915, 2018). "While FLT3 mutations are not directly associated with lymphomas, FLT3 mutations are frequently observed in acute myeloid leukemia and considered a negative prognostic factor for this disease." (PMID 29674676, 2018). "Subsequently, a dose-escalation study of ponatinib, with and without combination of 5-Azacytidine, in patients with FLT3-mutated acute myeloid leukemia was retired." (PMID 30423915, 2018). "In addition to mutations in the Shp2 gene, other leukemia associated mutations have been described that result in constitutive activity of Shp2, including internal tandem duplication of FLT3 in acute myeloid leukemia (AML) and expression of Bcr-abl in CML." (PMID 27769062, 2016). "Interestingly, in an independent study in hematopoietic cancer, the combination of JQ1 affecting the c-Myc levels and a FLT3 tyrosine kinase inhibitor (TKI) was synergistic in overcoming resistance to the FLT3 TKI in acute myeloid leukemia (AML) cells." (PMID 26284497, 2015). "Specifically related to acute myeloid leukemia, binding anti-FLT3 inhibitor drugs to nano-carriers might offer a new and exciting approach to an improved treatment." (PMID 26625890, 2015).
acute myeloid leukemia (continued). "De novo acute myeloid leukemia (AML) with concurrent DNMT3A, FLT3 and NPM1 mutations (AMLDNMT3A/FLT3/NPM1) has been suggested to represent a unique AML subset on the basis of integrative genomic analysis, but the clinical features of such patients have not been characterized systematically." (PMID 25281355, 2014). "Constitutive activation of PI3K/mTOR signaling occurs in the majority of human acute myeloid leukemia (AML) and likely results from a variety of mechanisms, including alterations in cellular growth factors and mutations in FLT3, c-kit, and Ras pathway proteins." (PMID 24904824, 2014). "The importance of DEP-1-FLT3 interaction is further supported by the observation that acute myeloid leukemia cells expressing the constitutively active FLT3 ITD mutant have a compromised DEP-1 activity due to reversible oxidation, a process which contributes to cell transformation." (PMID 23650535, 2013). "Other examples of deregulated tyrosine kinases fusion genes which are found in myeloid malignancies include TEL-ABL, TEL-JAK2, FLT3/ITD in acute myeloid leukemia (AML), ETV6-PDGFRB (TEL-PDGFRB) in chronic myelomonocytic leukemia (CMML), and FIP1L-PDGFRA in chronic eosinophilic leukemia (CEL)." (PMID 24116232, 2013). "Indeed, recent studies have reported on the roles of bone marrow-derived stromal cells in protecting myeloproliferative neoplasms or acute myeloid leukaemia from the effects of JAK2 or FLT3 tyrosine kinase inhibitors, respectively." (PMID 21897388, 2011). "Furthermore it is under clinical investigation in FLT3 positive acute myeloid leukemia (AML) patients." (PMID 20950443, 2010). "We investigated FMS-like tyrosine kinase 3/internal tandem duplication (FLT3/ITD+) in 40 adult patients with de novo acute myeloid leukemia (AML), categorized according to cytogenetic results, from September 2001 to May 2005." (PMID 19466291, 2009). "We describe a 60-year-old man with FLT3-ITD-mutated acute myeloid leukemia (AML) who achieved durable remission following venetoclax-based therapy and a combined HLA-matched sibling HCT-kidney transplant with FLT3 inhibitor maintenance." (PMID 42231121, 2026). "An integrated transcriptomic and survival analysis led to the identification of SYK and HDAC isoforms as age- and FLT3-dependent prognostic markers in acute myeloid leukemia (AML)." (PMID 42262889, 2026). "Acute myeloid leukemia (AML) patients with FMS-like tyrosine kinase 3 (FLT3) internal tandem duplications cells showed high activity of ETC complex II and correspondingly high mitochondrial respiratory activity." (PMID 40801609, 2025). "For example, aberrant DDR activation has been linked to resistance in acute myeloid leukemia (AML) and chronic myeloid leukemia (CML), with FLT3-ITD and Bcr-Abl mutations conferring resistance to tyrosine kinase inhibitors (TKIs) such as imatinib." (PMID 40703657, 2025). "The FLT3-ITD mutation serves as a critical driver mutation in the pathogenesis and progression of acute myeloid leukemia (AML) and represents a key focus for the development of anti-AML targeted therapies." (PMID 40710514, 2025). "Additionally, acute myeloid leukemia with NPM1 mutations (without FLT3–ITD) or in-frame CEBPA mutations in the basic leucine zipper region is now categorized as favorable-risk due to its heightened sensitivity to chemotherapy." (PMID 40362596, 2025). "Despite the initial promise of FLT3 inhibitors, the discouraging outcomes in the treatment of FLT3-ITD-positive acute myeloid leukemia (AML) promote the pursuit of more potent and enduring therapeutic approaches." (PMID 39885312, 2025).
acute myeloid leukemia (continued). "Targeting both FLT3-Wild Type and mutant FLT3 is a viable method for the treatment of Acute Myeloid Leukemia (AML) due to the significance of FLT3 in this condition." (PMID 41471328, 2025). "Derivative 63 exhibited a good anti-proliferative impact against FLT3-ITD positive acute myeloid leukemia (AML) cell lines, with MV4-11 IC50 = 38.8 ± 10.7 nM and MOLM-13 IC50 = 54.9 ± 4.1 nM." (PMID 41471328, 2025). "In acute myeloid leukemia (AML), the increase d expression of PDP1 is associated with metabolic reprogramming following FLT3 inhibition." (PMID 40337509, 2025). "The internal tandem duplication mutation of FMS-like tyrosine kinase 3 (FLT3-ITD) is associated with high recurrence and mortality rates in acute myeloid leukemia (AML), making it a critical target for anti-AML therapies." (PMID 40710514, 2025). "We found that ATG4B exhibited significantly high expression levels in various acute myeloid leukemia (AML) with diverse molecular subgroups (e.g., MLL‐rearrangement, FLT3‐ITD mutation, and NPM1 mutation, etc.)." (PMID 40788108, 2025). "This study evaluated the effectiveness of gilteritinib combined with venetoclax in patients with relapsed/refractory (R/R) acute myeloid leukemia (AML) or myelodysplastic neoplasms (MDS) with wild-type FLT3, who currently lack targeted therapy." (PMID 41199910, 2025). "Activating mutations in FLT3, particularly internal tandem duplications (FLT3-ITD), confer a poor prognosis in acute myeloid leukemia (AML)." (PMID 41590715, 2025). "We previously reported MA49 as a highly potent VHL‐mediated PROTAC candidate with potential for the treatment of FLT3‐ITD‐driven acute myeloid leukemia (AML)." (PMID 40223615, 2025). "Internal tandem duplication in FMS-like tyrosine kinase 3 (FLT3/ITD) is a common type of activating mutation and frequently detected in acute myeloid leukemia (AML)." (PMID 40263296, 2025). "Targeting FLT3 is crucial in acute myeloid leukemia (AML) treatment, with inhibitors like midostaurin, gilteritinib, and quizartinib available." (PMID 40427072, 2025). "This study aims to explore the impacts of FLT3 mutations in pediatric acute lymphoblastic leukemia (ALL) and acute myeloid leukemia (AML) and to compare the mutation profiles between the two types to inspire the targeted application of FLT3 inhibitors." (PMID 39273530, 2024). "Gilteritinib is a tyrosine kinase inhibitor (TKI) that treats acute myeloid leukemia (AML) by inhibiting FMS-like tyrosine kinase 3 (FLT3)." (PMID 39473682, 2024). "Last but not least, the FLT3‐based treatment is well researched and widely used in FLT3‐mutated acute myeloid leukemia, which may facilitate simple application to solid tumors." (PMID 38327131, 2024). "During the treatment of 89 pediatric patients with Acute Myeloid Leukemia (AML) at the Hematology Department of Kunming Medical University’s Children’s Hospital from 2020 to 2023, three patients were identified to co-express the NUP98-NSD1, FLT3-ITD, and WT1 gene mutations." (PMID 39068406, 2024). "Other proteins of this pathway that interact with SP1 include FLT3 which is important for the normal development and the immune system and is a drug target for acute myeloid leukemia (AML).68." (PMID 38410465, 2024). "Moreover, CEBPA-dependent expression of Fms related receptor tyrosine kinase 3 (FLT3) renders acute myeloid leukemia cells vulnerable to ferroptosis upon inhibition of FLT3, suggesting a therapeutic potential for targeting this pathway in acute myeloid leukemia treatment." (PMID 38844964, 2024). "Acute myeloid leukemia (AML) with fms-like tyrosine kinase 3 internal tandem duplication (FLT3-ITD) has poor outcomes." (PMID 38284896, 2024). "In pediatric acute myeloid leukemia (AML), co-expression of NUP98-NSD1 and FLT3-ITD gene abnormalities are frequently associated with poor prognosis." (PMID 39068406, 2024).
acute myeloid leukemia (continued). "Midostaurin is the first oral multitargeted TKI (tyrosine kinase inhibitors) to improve overall survival in patients with FLT3-mutant AML (acute myeloid leukemia) and represents an important addition to the limited armamentarium against AML." (PMID 38474445, 2024). "Indeed, SIRT1 was shown to promote leukemogenesis in CML and FLT3-ITD acute myeloid leukemia (AML)." (PMID 39479446, 2024). "This study investigates a dual-targeting strategy in acute myeloid leukemia (AML), focusing on FLT3 and CD99." (PMID 39007347, 2024). "Activating mutations of FLT3 contribute to deregulated hematopoietic stem and progenitor cell (HSC/Ps) growth and survival in patients with acute myeloid leukemia (AML), leading to poor overall survival." (PMID 38950330, 2024). "Previous studies showed indeed that FLT3-driven acute myeloid leukemia (AML) cells exposed to FLT3 inhibitors together with the inhibition of the ATM/G6PDH axis showed a higher response to therapy." (PMID 37932830, 2023). "FYN expression is dysregulated in acute myeloid leukemia (AML) patient samples, and FYN is associated with wild-type FLT3 and oncogenic FLT3-ITD." (PMID 36740671, 2023). "For example, internal tandem duplication within FLT3 (FLT3-ITD) confers constitutive activation of FLT3, represents one of the most frequent mutations in acute myeloid leukemia (AML), and correlates with a poor prognosis." (PMID 37759431, 2023). "FLT3 often undergoes changes that contribute to the onset of a blood cancer known as acute myeloid leukemia (AML)." (PMID 38001685, 2023). "FMS-like tyrosine kinase 3 (FLT3) inhibitors represent the new standard of care for patients with FLT3-mutant acute myeloid leukemia (AML), in both the first line and salvage settings." (PMID 37239765, 2023). "25–30% of younger adults with newly diagnosed acute myeloid leukemia (AML) carry internal tandem duplications (ITDs) in the FLT3 gene." (PMID 36966261, 2023). "The SPC839 is a dual inhibitor of AP-1 and NF-κB, showed good inhibitory activity against nitric oxide, TNF-α and FLT3, which is a potential target for acute myeloid leukemia (AML)." (PMID 37483616, 2023). "These have been stimulated kinases, like epidermal growth factor receptor (EGFR) in melanoma, B-Raf proto-oncogene, serine/threonine kinase (BRAF) in pulmonary cancer, and fms-like tyrosine kinase 3 (FLT3) in acute myeloid leukemia (AML) cases." (PMID 37062547, 2023). "Sorafenib therapy improves overall survival (OS) in patients with FLT3 internal tandem duplication (ITD) acute myeloid leukemia (AML) undergoing allogeneic hematopoietic stem cell transplantation." (PMID 37704613, 2023). "Internal tandem duplications (ITDs) of the FLT3 gene are observed in about 25% of young adults with newly diagnosed acute myeloid leukemia (AML)." (PMID 36509894, 2023). "Moreover, compound 27 affords powerful antineoplastic activity versus FLT3-ITD acute myeloid leukemia cells, including MV4-16, and MOLM-18 with IC50s equal to 38.8 and 54.9 nM, respectively, whereas no fundamental potency versus acute myeloid leukemia cells deficient of FLT3-ITD." (PMID 37438819, 2023). "Using GAB2 deficient mice, we previously showed that GAB2 serves as an important effector of the oncogenic FLT3-ITD receptor tyrosine kinase in acute myeloid leukemia (AML) and of BCR::ABL1 in CML." (PMID 37161070, 2023).